RN7SKP162 (RN7SK pseudogene 162)
Gene: Miscellaneous RNA gene on chromosome 12 (13,683,542 to 13,683,886, forward strand). Ensembl gene ENSG00000200475.
Homologues: Orthologues: chimpanzee 7SK (94% identical). Paralogues in human: RN7SKP296 (70% identical), RN7SKP203 (69% identical), RN7SKP217 (69% identical), RN7SKP133 (69% identical), RN7SKP184 (68% identical), RN7SKP90 (68% identical), RN7SKP180 (68% identical), RN7SKP225 (68% identical), RN7SKP33 (68% identical), 7SK (67% identical), RN7SKP249 (67% identical), RN7SKP47 (67% identical), and 283 more.